MIR424 (microRNA 424)
Synonyms: hsa-mir-424; MIR322; MIRN424; miRNA424; mir-424
Gene: MicroRNA gene on chromosome X (134,546,614 to 134,546,711, reverse strand). Ensembl gene ENSG00000284231.
Gene Ontology:
Biological process: miRNA-mediated post-transcriptional gene silencing
Cellular component: RISC complex
Homologues: Orthologues: chimpanzee ptr-mir-424 (100% identical), macaque MIR424 (100% identical), guinea pig MIR424 (81% identical), pig ssc-mir-424 (74% identical), mouse Mir322 (71% identical).